CYLD (CYLD lysine 63 deubiquitinase)
Diseases named in the same sentence as CYLD in open-access papers (continued):
Sharing a sentence is not in itself a finding about the gene and the disease.
tumor (continued). "Interestingly, in line with its potential function as a tumor suppressor, low CYLD expression significantly correlates with poor overall survival in DLBCL and MCL." (PMID 36922488, 2023). "Several necroptosis-related molecules were downregulated in tumor cells, such as CYLD." (PMID 37169000, 2023). "CYLD is a tumor suppressor gene coding for a deubiquitinating enzyme that has a critical regulatory function in a variety of signaling pathways and biological processes involved in cancer development and progression, many of which are also key modulators of somatic cell reprogramming." (PMID 37894364, 2023). "SPATA2 and CYLD deficiency significantly reduced tumor growth in BALB/c mice but not in Rag2-/- BALB/c mice, suggesting that adaptive immune cells were required for tumor regression." (PMID 36531014, 2022). "The results indicated that tumors from the lncRNA GAS5-transfected GH3 cells grew more slowly than those from the control group during the entire tumor growth period, while miR-27a-5p mimics or silenced CYLD attenuated the effect of lncRNA GAS5 on tumor growth." (PMID 35435104, 2022). "Finally, we assessed if ablation of SPATA2 and CYLD can ameliorate immune exclusion in CRC tumors by evaluating tumor growth and intratumoral immune infiltration in BALB/c mice implanted with Spata2-KO, Cyld-KO, or WT CT26 cells." (PMID 36531014, 2022). "However, the NF-κB Activity Classifier identified many samples in the NF-κB “active” category that do not follow this clear-cut pattern, in particular identifying that simultaneous shallow deletion of TRAF3 and CYLD in a tumor correlated with NF-κB activity." (PMID 35634245, 2022). "CYLD is an already recognized tumor suppressor in several different tumors." (PMID 35956111, 2022). "CYLD is a K63-specific deubiquitinase that functions as a tumor suppressor in many cancers." (PMID 36185211, 2022). "We therefore hypothesized that increased T-cell chemokine expression upon ablation of SPATA2 or CYLD is driven by elevated IFN-γ-STAT1 signaling in tumor cells." (PMID 36531014, 2022). "In addition, CYLD regulates CXCL5 production by inhibiting NF-ĸB, thus affecting the migration of tumour-associated neutrophils." (PMID 35579924, 2022). "In two oral tongue squamous cell carcinoma (OTSCC) cell lines CAL-27 and SSC-4, cylindromatosis (CYLD), which acts as a tumor suppressor in several malignancies and is responsible for cisplatin resistance in OSCC patients, has been proved to be one of the multiple target genes of miR-130a." (PMID 33953745, 2021). "In summary, CYLD, as a tumor-suppressing DUB, has a close relationship with CSCs." (PMID 34179009, 2021). "Overall, CYLD loss led to increased PD-L1 expression in TET cells through both these cascades, with a significant correlation between low IHC CYLD expression and high PD-L1 expression (tumor proportion score ≥ 50%)." (PMID 33915954, 2021). "CYLD is considered to be a tumor suppressor widely existing in a variety of tumors." (PMID 33827598, 2021). "However, the in vivo role of CYLD as a tumor suppressor of skin squamous cell tumors in immunocompetent mice has not yet been elucidated." (PMID 34201751, 2021). "Then two NPC tumor tissue microarrays were used to investigate the prognostic role of CYLD." (PMID 33654169, 2021). "Accumulating evidence has established the tumour-suppressive role of CYLD." (PMID 35008337, 2021). "In addition to affecting NF-κB signaling, CYLD loss or low expression also sensitizes MM cells to Wnt ligands, indicating another possible tumor-suppressive mechanism of CYLD in MM." (PMID 34454635, 2021). "This analysis may enhance tumor categorization and inform further correlations with prognosis and potential therapeutic approaches to CYLD-mutant tumors, such as recently investigated targeted inhibitors for cylindromatosis." (PMID 32892208, 2021).
tumor (continued). "In addition, the correlation of CYLD downregulation with tumor development and progression of many types of cancers such as hepatocarcinoma, colon, and breast tumors has also been described." (PMID 34201751, 2021). "Knockdown of CYLD resulted in increased proliferation and overexpression of p18 reversed this tumor-promoting effect in vitro and in vivo, indicating that CYLD exerts its tumor suppressor function dependent on p18." (PMID 33654169, 2021). "CYLD localized to both the cytoplasm and cell membrane in tumour cells." (PMID 35008337, 2021). "Overexpression of CYLD in EBV ( + ) NPC cells markedly inhibited tumor growth in athymic nude mice." (PMID 33654169, 2021). "More than just a tumor suppressor, CYLD has many potential functions." (PMID 33982884, 2021). "As a mechanism of this tumor suppressor activity, we found that a moderate increase in CYLD expression levels reduced NF-κB activation, which favored the differentiation of tumor epidermal cells and inhibited its proliferation; moreover, it decreased tumor angiogenesis and inflammation." (PMID 34201751, 2021). "Additionally, sh-SOX2 treatment decreased mRNA expression of SOX2, CCAT1, EGFR, and miR-222-5p in tumor isolated from nude mice, but increased the mRNA expression of CYLD." (PMID 33952719, 2021). "CYLD was first identified in familial cylindroma and was shown to be a tumor suppressor." (PMID 33827598, 2021). "Overall, our data demonstrate that CYLD exerts a p18-dependent tumor-suppressing function." (PMID 33654169, 2021). "Importantly, YTHDC2 functions as a tumor suppressor through the CYLD/NF-κB signaling pathway, which is mediated by m6A modification." (PMID 34326699, 2021). "Knockout of CYLD results in hyperactive NF-kB activity, which may regulate the host immune response, resulting in altered stromal cell composition to support tumor growth." (PMID 32708712, 2020). "Thus, CYLD appears to inhibit NPC tumor recruitment of stromal cells, including fibroblasts and endothelial cells into the TME." (PMID 32708712, 2020). "Nevertheless, the ubiquitination of AKT can be reversed by CYLD, which is a deubiquitinating enzyme and plays a tumor suppressor role in inhibiting AKT activity by removing AKT K63-linked ubiquitin chains and serves as a negative regulator for AKT-mediated tumorigenesis or lung fibrosis." (PMID 31988639, 2020). "CYLD is a tumor suppressor that deubiquitinates K63 chains directly downstream of TNFα receptors." (PMID 32602581, 2020). "The generation of mutant CYLD-/- mice has confirmed the role of this DUB as a tumor suppressor." (PMID 32549302, 2020). "Only 8% (n = 34) of the CYLD-wildtype cases showed aggregates of tumor cells containing round fragments of hyalinized material, consistent with basement membrane inclusions, imparting a cylindroma-like appearance similar to the CYLD-mutant cases." (PMID 32461623, 2020). "While there are limitations with the pharmacological and dominant-negative approaches used in this study, nonetheless the observations strongly suggest that phosphorylation of CYLD is a mechanism used by ATLL cells to suppress this tumor suppressor and maintain tumor cell survival." (PMID 32024820, 2020). "Surprisingly, 13% of our cohort of ACs carried CYLD mutations, and those tumors show near-universal detection of high-risk HPV sequences, low tumor mutational burden, and, predominantly, a striking cylindroma-like histopathology with characteristic hyaline globule inclusions." (PMID 32461623, 2020). "Moreover, we propose that this is an important mechanism through which CYLD exerts its function as a tumor suppressor." (PMID 30631004, 2019). "Both tumor samples showed an identical 25–base pair deletion in exon 19 of CYLD, with LOH." (PMID 31085270, 2019). "Although in tumor tissues only LYVE-1 expression is significantly upregulated, there is a notable tendency of higher expression of nearly all markers after loss of CYLD, which supports the role of CYLD in regulating lymph angiogenesis." (PMID 31591386, 2019).
tumor (continued). "Additionally, a tumor suppressor function of CYLD has been described in several other malignancies, such as melanoma, salivary gland cancer, cervical cancer, hepatocellular carcinoma, and lung cancer." (PMID 31795161, 2019). "We reasoned that CYLD, a tumor suppressor that is an inhibitor of NF-κB activation, and consequently of inflammation, could also play an important role against aging." (PMID 30631004, 2019). "Thereby, the study of the K5-CYLDC/S mice demonstrates the essential role of CYLD, in vivo, as a tumor suppressor of wide spectrum, providing an excellent model for studying, in vivo, the signaling pathways throughout CYLD exerts its tumor suppressor role in different types of cancer." (PMID 30631004, 2019). "In addition, the level of miR-499-5p in xenograft tumor was decreased markedly and the CYLD level in xenograft tumor was dramatically elevated in pcDNA-MEG3 group compared with normal control group and pcDNA-control group." (PMID 29808164, 2018). "CYLD was originally reported as a tumor suppressor and later characterized as a deubiquitinase." (PMID 30388174, 2018). "It is intriguing to consider whether CYLD acts as a tumor suppressor by potentiating STING signaling in cancer." (PMID 30388174, 2018). "It is also reported that a tumor suppressor CYLD deubiquitinase inhibits the ubiquitination of Dvl." (PMID 27536874, 2016). "Since AOM and DMBA are genotoxic agents, we reasoned that CYLD activity might increase DNA damage-induced cell death and therefore suppress tumour development by regulating the DNA damage response in epithelial cells." (PMID 27561390, 2016). "CYLD functions as a tumor suppressor through negative regulation of NF-κB pathway." (PMID 26950276, 2016). "CYLD is a deubiquitinase known to act as a tumour suppressor in different models of carcinogenesis." (PMID 27561390, 2016). "Nevertheless, the mechanisms of CYLD-mediated tumour suppression remain poorly understood." (PMID 27561390, 2016). "To dissect whether CYLD suppresses colon tumorigenesis by preventing AOM-mediated tumour initiation or DSS-induced tumour promotion, we first studied the response of CYLDΔ932IEC mice to DSS." (PMID 27561390, 2016). "It is also possible that hair follicle stem cells that harbor CYLD alterations may acquire additional genetic changes over one’s lifetime thus resulting in tumor formation." (PMID 31093340, 2016). "Using a subcutaneous tumor model, the authors demonstrated that the CYLD mutant tumors not only grew faster and larger in size, but also showed a more aggressive, poorly differentiated phenotype when compared to the control tumors which bore a less aggressive, differentiated phenotype." (PMID 31093340, 2016). "Besides the published HNSCC TCGA dataset, a recent study has identified a high incidence of CYLD aberrations in a rare salivary gland tumor, namely the dermal analogue tumor, which can be of sporadic or familial origins." (PMID 31093340, 2016). "Furthermore, transgenic expression of catalytically inactive mutant CYLD in the epidermis also sensitized mice to DMBA/TPA-induced skin tumorigenesis." (PMID 27561390, 2016). "Cylindromatosis (CYLD), a deubiquitinase, is originally identified as a tumor suppressor." (PMID 27738385, 2016). "To test whether CYLD regulates carcinogen-induced tumour formation in other epithelia, we generated mice expressing the catalytically inactive CYLDΔ932 mutant in epidermal keratinocytes (CYLDΔ932epi) by crossing CYLDΔ932FL mice with K14-Cre transgenics." (PMID 27561390, 2016). "CYLD, a tumor suppressor, regulates the apoptotic process, proliferation, and cell cycle." (PMID 27821810, 2016). "Both A20 and CYLD have been shown to act as tumor suppressors in different cell types." (PMID 27134758, 2016).
tumor (continued). "CYLD-deficient mice did not develop spontaneous tumours but showed increased susceptibility in different models of carcinogenesis." (PMID 27561390, 2016). "Importantly, mice with homozygous as well as heterozygous loss of CYLD (i.e. CYLD−/− and CYLD+/− mice) both developed multiple tumor phenotype on the skin much earlier than the CYLD+/+ mice." (PMID 31093340, 2016). "Importantly, nuclear CYLD inversely correlated with both tumor grading and Ki67 positivity in HCC patients." (PMID 25329885, 2014). "In particular, RUNX1 was overexpressed in CYLD defective tumour cells." (PMID 25565632, 2014). "Expression of HEY1 transcript was assessed in 15 CYLD defective tumours." (PMID 25565632, 2014). "CYLD (the familial cylindromatosis tumor suppressor gene) enhances the activation of the transcription factor NFkapa-B, RBBP6, (which binds to the retinoblastoma gene product pRB), and PNUTL2 (which is an apoptosis-related protein in the TGF-beta signaling pathway)." (PMID 23056957, 2012). "Also supporting this line of evidence is the finding that the tumor suppressor CYLD blocks cyclin D1 expression by inhibiting Bcl-3 signaling." (PMID 20731879, 2010). "Notably, as the sole protective NRG for LUAD, CYLD Lysine 63 Deubiquitinase (CYLD) had been considered as the tumor suppressor and further demonstrated to be regulated by miR-96-5p and LncRNA GMDS-AS1 to inhibit the development of LUAD via a cellular assay and mouse tumor models." (PMID 35754848, 2022). "Interestingly, CYLD deficiency has been shown to promote PCa cell proliferation, cell survival, and tumorigenesis, and CYLD abundance is reduced in advanced-stage PCa samples, suggesting that CYLD may play a tumour-suppressive role in PCa." (PMID 36009554, 2022). "Therefore, we hypothesized that SPATA2 and CYLD are suppressing chemokine production in tumor cells by modulating NF-κB and/or STAT1 signaling." (PMID 36531014, 2022). "Moreover, SPATA2 and CYLD deficiency did not significantly impact tumor-intrinsic fitness, as evidenced by comparable cell proliferation kinetics in vitro between KO and WT cells." (PMID 36531014, 2022). "Moreover, YTHDC2 may serve as a tumor suppressor via the m6A-mediated CYLD lysine 63 deubiquitinase/NF-κB regulatory signaling pathway." (PMID 36581942, 2022). "Importantly, restoring p18 expression fully reversed the tumor-promoting effect of CYLD shRNA." (PMID 33654169, 2021). "It is relevant that the in vivo role of CYLD as a tumor suppressor of NMSC has only been analyzed through the study of transgenic mice that either contain a functionally inactive CYLD (by expression of mutated forms of CYLD that act as dominant negative) or that are deficient in CYLD." (PMID 34201751, 2021). "Therefore, our data in the present work suggest that a moderate increase in CYLD levels in keratinocytes is able to inhibit inflammation and angiogenesis in skin squamous cell tumors and then act as a tumor suppressor of this type of NMSC in mice with an undamaged immune system." (PMID 34201751, 2021). "The incidence and growth rates of tumors in CYLD+/‐ mice significantly increased and were in‐between those of CYLD+/+ and CYLD‐/‐, indicating a potential dose effect of the CYLD gene on the proliferation of tumor cells (Masoumi, Shaw‐Hallgren, & Massoumi, 2011)." (PMID 32783365, 2020). "In addition, our results suggest that the role of CYLD as an aging suppressor may be a mechanism through which CYLD acts as a tumor suppressor." (PMID 30631004, 2019). "Thus, CYLD plays a critical role in the suppression of tumor proliferation." (PMID 29259980, 2017). "However, the tumour suppressing mechanisms of CYLD remain poorly understood." (PMID 27561390, 2016). "CYLD deactivation could provide specific advantage to tumour cells by enhanced NF-κB signalling." (PMID 27597804, 2016).
tumor (continued). "CYLD was recently shown to regulate death receptor-induced apoptosis and necroptosis, suggesting that regulation of death receptor- mediated programmed cell death could also contribute to its tumour suppressing functions." (PMID 27561390, 2016). "Interestingly, tumor suppressor CYLD acts as a negative regulator for the synergistic induction of inflammation by S. pneumoniae and NTHi, thereby implying a critical role for CYLD in preventing overactive inflammatory response in mixed infections." (PMID 18664270, 2008). "Residing on 16q are many notable tumor suppressor genes including LC3B, CYLD, CDH11, CDH1, ZFHX3, CREB, CTCP, and all metallothioneins (MTs), which emerging research indicates are also tumor suppressors." (PMID 40565600, 2025). "CYLD DUB activity is inhibited by S418 and S422 phosphorylation, and thus our data indicates that CYLD inhibition promotes tumor resistance to T cell killing." (PMID 41315176, 2025). "Our findings offer novel insight into the function of CYLD in tumor and uncover important roles for CYLD-HDAC axis in radiosensitivity, which provide new molecular target and therapeutic strategy for tumor radiotherapy." (PMID 38287022, 2024). "Next the relationship of ZNF202 and CYLD was analyzed by IHC in NPC tissues and a tumor tissue microarray." (PMID 38287022, 2024). "IHC results demonstrated that the expression levels of CDH4, CYLD, and STAT4 were stronger in adjacent basal epithelium compared to that in tumor cells (p < 0.001)." (PMID 37393410, 2023). "By specifically deleting SPATA2 and CYLD in human and mouse CRC cell lines, we showed that these two proteins inhibit STAT1 accumulation and activation and subsequently CXCL10 expression in tumor cells." (PMID 36531014, 2022). "Genetic ablation of SPATA2 or CYLD in murine CRC tumors increased CXCL10 expression and T cell accumulation in the TME, concomitant with retarded tumor growth." (PMID 36531014, 2022). "Here we showed a redundant role of SPATA2 and CYLD in the regulation of STAT1 activation and IFN-γ-induced genes in tumor cells." (PMID 36531014, 2022). "In summary, we identified SPATA2 and CYLD as novel regulators of T/NK cell-attracting chemokines CXCL9, CXCL10, CXCL11 in tumor cells." (PMID 36531014, 2022). "In both NPC tissues and the tumor tissue microarray, increased EAD positivity was more frequently observed in CYLD-low expressing group than in CYLD-high expressing group." (PMID 33654169, 2021). "Compared with empty vector infected cells, the mice injected with CYLD expressing HONE1-EBV cells showed increased CYLD activity and decreased tumor growth throughout the experiment." (PMID 33654169, 2021). "Downstream, K63-Ub/SQSTM1 accumulation results in the sequestration of damaged mitochondria, the CYLD K63 DUB, and the activation of the K63-Ub TRAF6-NF-κB pathway, providing metabolic, survival, inflammatory, and proliferative advantages to tumor cells." (PMID 34065348, 2021). "Our study is the first to demonstrate CYLD modulates fibroblast and endothelial cell infiltration in the NPC tumor microenvironment in addition to inhibiting tumorigenicity and metastasis." (PMID 32708712, 2020). "Tumor-activated neutrophils release BMP2 to trigger the expression of miR-301-3p in HCC cells, which down-regulates LSAMP and CYLD expression to increase the stemness of HCC cells." (PMID 32632106, 2020). "The in vivo and in vitro assays suggest CYLD, as a negative regulator of the NF-kB signaling pathway in NPC, affects tumor growth, metastasis and the TME composition." (PMID 32708712, 2020). "Several studies implicate USP4, USP7, USP6, USP15, USP16, USP42, and USP28 as oncogenes, whereas CYLD, A20, and BAP1 act as tumor suppressors." (PMID 32549302, 2020). "We now report that phosphorylation of CYLD by IKK family kinases in HTLV-1 transformed T cells inhibits RIPK1 from activating the cell death pathway and inhibiting these kinases reactivates CYLD and RIPK1-dependent tumor cell death." (PMID 32024820, 2020).